TTF1 (transcription termination factor 1)
Diseases named in the same sentence as TTF1 in open-access papers (continued):
Sharing a sentence is not in itself a finding about the gene and the disease.
carcinoids (24 papers, 2011 to 2025). "IHC analysis revealed a similar immunophenotype of ovarian strumal carcinoid with normal thyroid tissue, wherein the strong positive reaction of thyroid-specific transcription factor-1 (TTF-1) and PAX8 was a significant feature." (PMID 41244794, 2025). "Consistently, among nine cases of strumal carcinoid tumors reported here, four were positive for TTF-1 and TG, two for TG alone, and one for TTF-1 alone (two cases were not tested)." (PMID 40069785, 2025). "The interface between struma ovarii and carcinoid showed strong PAX-8 and uniform TTF-1 staining in the struma but gradual loss of TTF-1." (PMID 40428242, 2025). "In contrast, the carcinoid was focally interspersed positive for TTF-1, patchy positive for CDX-2 and PAX-8, and CD56 (basal and cytoplasmic), strongly positive for synaptophysin, and negative for GATA-3, calretinin, and chromogranin-A." (PMID 40428242, 2025). "Of the nine cases of strumal carcinoid tumors, four were positive for both TTF-1 and TG, two were solely positive for TG, and one for TTF-1 only (the remaining two cases were not tested)." (PMID 40069785, 2025). "As expected, immunohistochemical evaluation confirms the duality of the disease, with expression of specific markers both of thyroid (thyroglobulin, TTF1, calcitonin) and carcinoid (chromogranin A, synaptophysin, NSE and CD56)." (PMID 35528006, 2022). "For lung NETs, TTF-1 expression in carcinoids is considered specific when compared with those of extra-pulmonary origin." (PMID 36233825, 2022). "Strumal carcinoids exhibit positive staining with neuroendocrine markers (carcinoid component) and thyroglobulin and thyroid transcription factor (TTF1) (thyroid component)." (PMID 34917031, 2021). "In the smaller carcinoids, expression of the neuroendocrine markers synaptophysin and chromogranin A was higher, but of TTF1 lower in comparison to LCNEC/SCLC." (PMID 25884169, 2015). "Carcinoids were smaller in size and had higher synaptophysin and chromogranin A, but lower TTF-1 expressions." (PMID 25884169, 2015). "Further investigations based on molecular and cellular analyses are required to determine a role of TTF-1 in SCLC as well as in carcinoid." (PMID 26705222, 2015). "Subsequent investigations, including immunohistochemical and ultrastructural studies, proposed a unified origin, showing co-expression of thyroid markers (such as TTF-1 and thyroglobulin) and neuroendocrine markers (synaptophysin, chromogranin-A) in the carcinoid areas or transitional zones." (PMID 40428242, 2025). "Furthermore, thyroid tissue within strumal carcinoid tumors expresses TTF-1 and TG, whereas carcinoid tissue lacks these markers." (PMID 40069785, 2025). "The predominance of TTF1 in carcinoids of bronchopulmonary origin was confirmed by other studies." (PMID 22269186, 2012). "In this regard, expression of TTF-1 may be helpful to identify a carcinoid tumor of lung origin, as carcinoid tumors from other sites rarely express this marker." (PMID 22263108, 2012). "It is important to recall that lung NETs/carcinoids can be positive for calcitonin, so the search for CEA expression (only positive in medullary thyroid carcinoma) is essential in TTF1 metastatic NETs." (PMID 40668487, 2025). "Immunoreactivity for chromogranin A, synaptophysin, TTF-1, and pan-cytokeratins AE1–3 was documented in carcinoid component, while adenocarcinomatous component was positive only for TTF-1 and cytokeratins." (PMID 34926584, 2021). "Interestingly, a few cases of peripheral type carcinoid (TTF-1+/OTP+) occurred in central location, and likewise, central type carcinoid was not always exclusive to the central location; therefore, designation of central and peripheral for such tumors may not be completely appropriate." (PMID 29770932, 2018).
carcinoids (continued). "In such neoplasms, the thyroidal component exhibits immunoreactivity for thyroid transcription factor-1 (TTF-1) and thyroglobulin (TG), whereas these markers are not typically expressed in the carcinoid component." (PMID 40069785, 2025). "Thyroid tissue within strumal carcinoids was positive for both thyroid TTF-1 and TG, whereas the carcinoid component did not express these markers." (PMID 40069785, 2025). "TTF1 is negative in panNETs while it is positive in medullary thyroid carcinoma and in about 40% of lung NETs/carcinoids (most peripherally located)." (PMID 40668487, 2025). "Immunoreactivity for chromogranin A, synaptophysin, TTF-1, and pan-cytokeratins (AE1-3 clone) was observed in carcinoid component, while glandular component was positive only for TTF-1 and cytokeratins; cytokeratin 7 was selectively expressed in the adenocarcinomatous component." (PMID 34926584, 2021). "Among carcinoids, loss of cytosolic PTEN was predominantly found in TTF1-negative larger tumors of male patients." (PMID 25884169, 2015). "The renal masses were negative for TTF-1, napsin, chromogranin, and synaptophysin and had no histological appearance of carcinoids." (PMID 26609460, 2015). "As in our first case, in fact, TTF-1 staining alone often leads to misdiagnosis since it is not specific and may be present in primary adenocarcinomas, carcinoid tumors and metastatic thyroid carcinomas." (PMID 34071040, 2021). "In contrast to TTF-1, no reactivity with non-adenous lung carcinomas, such as neuroendocrine carcinomas, large-cell neuroendocrine carcinomas, as well as small-cell bronchial carcinoma and carcinoids, was observed." (PMID 21811254, 2011). "While TTF1 and caudal type homeobox 2 (CDX2) can assist in distinguishing between primary and metastatic carcinoid tumors, the distinction is not always marked." (PMID 40069785, 2025).
melanoma (22 papers, 2007 to 2025). A malignant, usually aggressive tumor composed of atypical, neoplastic melanocytes. "Conversely, exclusion markers like Ber-EP4, CK7, TTF-1, S100, and SOX10 were essential in ruling out basal cell carcinoma, adenocarcinoma, and melanoma." (PMID 40427131, 2025). "At the same time, exclusion markers like Ber-EP4, CK7, TTF-1, and S100 play an essential role in the differential diagnosis of SCC against entities such as adenocarcinomas, basal cell carcinomas, and melanomas." (PMID 40427131, 2025). "In the present study we analyzed HMB45, MelanA, SOX10, CK5/6, NapsinA, p63, and TTF-1 in a large cohort of NSCLC cases and demonstrate that expression of melanoma markers is rare." (PMID 30205833, 2018). "Furthermore, biomarkers such as TTF-1 and CDX-2 can be used to identify metastatic MCC, whereas LCA, CD99, S100, HMB-45, and SOX-10 can exclude lymphoma, Ewing sarcoma, and malignant melanoma." (PMID 41245381, 2025). "Other tumors on the differential, metastatic lung cancer, mesothelioma, melanoma, and primary adrenal gland tumor, were excluded by negative staining of tumor cells for TTF-1, napsin, calretinin, WT-1, pan-melanoma, SOX10, and synaptophysin." (PMID 32983683, 2020). "The tumor cells were positive for AE1/AE3, S-100 protein, melan A, HMB-45, synaptophysin, calcitonin, chromogranin A, melanoma, and thyroid transcription factor-1 (TTF-1) and negative for thyroglobulin." (PMID 30424779, 2018). "On the other hand, tumor cells stained negative for CK20, transcription termination factor 1 (TTF-1), melanoma antibody (HMB45) and CgA." (PMID 24884973, 2014). "Histological examination of the brain tumor showed neural differentiation markers (thyroid transcription factor 1 (TTF-1), cytokeratin 7 (CK7), AE1/AE3, and epidermal growth factor receptor (EGFR)) with negative melanoma markers." (PMID 39192931, 2024). "In our two cases, immunohistochemical staining demonstrated that the tumor cells expressed HMB45, S-100, pan melanoma and Vimentin, and did not express CK, EMA, CgA, Syn, HCG, HMW-CK, Desmin, SM-actin, TTF-1, and SCLC." (PMID 22992473, 2012).
metastatic tumors (19 papers, 2011 to 2025). "Bulky tumors were associated with local inflammatory factors, while early metastatic disease correlated with TTF1 positivity, elevated LDH, and oncogenic driver mutations, highlighting divergent underlying biology." (PMID 41374930, 2025). "Analyzing the disease control rate (DCR) in patients with metastatic disease (stage IV), we observed a significantly (p = 0.006) improved response to treatment in the group of patients with TTF-1-expression (DCR 86% vs. 56%)." (PMID 25889870, 2015). "The present case showed TTF-1 negativity, indicating a poorer prognosis and consistent with advanced metastatic disease at presentation." (PMID 26316932, 2011). "TTF-1 together with SP-B might be useful in distinguishing between primary mucoepidermoid carcinomas of the lung and metastatic tumors from other regions." (PMID 23043986, 2012). "Both S.KPP and C.KPP demonstrate heightened TTF-1 and Napsin A expression when compared to no cancer controls, specifically in/around primary and metastatic tumors." (PMID 40021683, 2025). "GATA3, TTF-1, S100, p40, PAX8, p63, NKX3.1, CDX2, SALL4, CD30 (-) were detected to rule out metastatic disease." (PMID 40978995, 2025). "All cases histologically resembled well-differentiated NETs of visceral origin with Ki-67 proliferation indices of 5–42% and expression of T-PIT; metastatic tumors were not immunoreactive with CDX2, Islet 1 or TTF-1." (PMID 32622369, 2020).
lung squamous cell carcinoma (18 papers, 2013 to 2026). "TTF-1 expression was also present in 5 (8.9%) cases, and Napsin-A expression in 2 (3.6%) cases of lung squamous cell carcinoma but with the immunohistochemical score of 1+." (PMID 29317712, 2018). "On the immunostains, tumoral cells were positive for p40 and CK5/6 and negative for TTF1 and napsin A, sustaining the diagnosis of lung squamous cell carcinoma with acantholytic features (in context)." (PMID 38256374, 2024).
mucinous adenocarcinoma (18 papers, 2011 to 2025). An invasive adenocarcinoma composed of malignant glandular cells which contain intracytoplasmic mucin. "Approximately half of the HNF4α-positive non-mucinous adenocarcinomas were TTF-1-positive (7/15, 47%), and they frequently showing papillary predominant histology (6/7, 86%)." (PMID 38710944, 2025). "Transgenic mice with inactivated Nkx2-1/Ttf-1 develop mucinous adenocarcinomas in the lungs that resemble human IMAs." (PMID 34290355, 2022). "The KRAS mutated LADCs grow in a solid pattern with TTF1 positivity (thyroid transcription factor) while the mucinous adenocarcinoma histology lacks TTF-1." (PMID 34918209, 2021). "In contrast to mucinous adenocarcinoma, all cases examined in this study showed diffuse TTF-1 positivity and one case showed possible overexpression." (PMID 28830562, 2017). "In conclusion, a subset of HNF4α-positive adenocarcinomas, such as mucinous adenocarcinomas with gastrointestinal differentiation, are TTF-1-negative and SMARCA4 retained, often showing KRAS mutations." (PMID 38710944, 2025). "Moreover, TTF-1-negative and HNF4α-positive non-mucinous adenocarcinomas showed wild-type EGFR and frequent SMARCA4 loss, and tended to show a high-grade solid morphology and very poor prognosis." (PMID 38710944, 2025). "It was believed that TTF‐1 might be expressed in mucinous adenocarcinoma." (PMID 38616354, 2024). "Besides, the deletion of TTF-1 seems to induce the phenotype of mucin through the subsequent release of Foxa1/Foxa2, and human lung infiltrating mucinous adenocarcinomas almost always express HNF4A and have a significant connection with negative TTF-1 expression and positive KRAS mutation status." (PMID 34631891, 2021). "Also, positive TG and TTF-1 staining confirmed that the tumor originated from the thyroid gland and had the ability to differentiate into thyroid tissue, thus ruling out the possibility of a thyroid metastasis from a mucinous carcinoma of another organ." (PMID 27282149, 2016). "All cases of mucinous, enteric, and colloid adenocarcinoma were HNF4α-positive, TTF-1-negative, and SMARCA4 retained, and showed a high frequency of KRAS mutations (10/18, 55.6%) and no EGFR mutations (0/18, 0%)." (PMID 38710944, 2025). "Prior studies have reported TTF1 sensitivity for adenocarcinoma in a range of 75 to 86%.12, 13, 14, 15, 16, 17, 18In the well-differentiated adenocarcinomas, four cases which were negative for TTF1 revealed morphological features of mucinous adenocarcinomas." (PMID 39584166, 2024). "Four cases of adenocarcinoma which were negative for TTF1 staining were mucinous adenocarcinoma on morphology, as Napsin A was strongly positive in all these cases." (PMID 39584166, 2024). "Although TTF1 is shown to be absent in invasive mucinous adenocarcinoma of the lung, these neoplastic lesions in the lungs of FILIP1L-knockout mouse demonstrated strong mucin secretion." (PMID 36860703, 2022). "However, the expression of TTF-1 rate is different in the IMA, and its expression rate in IMA is often lower than that in non-mucinous adenocarcinoma." (PMID 31292000, 2019). "revealed, invasive mucinous adenocarcinoma was mostly negative for TTF-1, which was in consistence with our results." (PMID 29296178, 2017). "The neoplastic cells of metastatic prostatic adenocarcinoma were positive for NKX3.1 and PSA, negative for CDX‐2, CK7, and TTF1; whereas the neoplastic cells of lung mucinous adenocarcinoma were positive for CDX2, CK7, and napsin‐A (focal), negative for TTF1, NKX3.1, and PSA." (PMID 40028792, 2025). "We underline the difficulty of the clinical pre-operative diagnosis of this cystic neoplasia radiologically mimicking a hydatid cyst, and we report the negative TTF1 immunostaining potentially misleading in the differential diagnosis with metastatic mucinous carcinomas." (PMID 21970610, 2011).
mucinous adenocarcinoma (continued). "Moreover, in our opinion, negative TTF1 immunostainig in lung mucinous carcinomas, potentially misleading in the differential diagnosis from metastatic mucinous carcinomas, has not been adequately stressed in literature." (PMID 21970610, 2011). "Colloid carcinomas are generally positive for CK7 and CDX2 and weak or negative for TTF1, napsin A and EMA (MUC1)." (PMID 41473421, 2025). "In addition, some conventional non-mucinous adenocarcinomas are HNF4α-positive, which include not only TRU-type adenocarcinomas that are double-positive for TTF-1 and HNF4α but also non-TRU-type poorly differentiated (grade 3) adenocarcinomas with frequent loss of SMARCA4 expression." (PMID 38710944, 2025).
anaplastic thyroid carcinoma (17 papers, 2012 to 2025). "PAX8 staining (seen in 36–76% cases), TTF1 and focal keratin positivity also helps in confirming an anaplastic carcinoma of thyroid." (PMID 38438897, 2024). "In the ARO anaplastic thyroid carcinoma cell line, the upregulation of TTF-1 increased the cell doubling time, cell migration and in vivo cell growth (in a nude mice model)." (PMID 36551653, 2022). "Anaplastic thyroid carcinoma was diagnostically excluded because of the colloid production, only mild nuclear pleomorphism, and diffuse TTF1 and PAX8 reactivity." (PMID 34997561, 2022). "C643 cells isolated from anaplastic thyroid cancer and having a highly undifferentiated status showed a high or basal expression of TTF1, even after treatment with HDACi." (PMID 29561759, 2018). "DNA methylation suppresses the expression of thyroid transcription factor‐1 (TTF‐1) in 60% of undifferentiated thyroid carcinomas." (PMID 24963031, 2014). "Lack of nuclear beta-catenin expression in the stroma, lack of follicular epithelial differentiation, positivity for PAX8 and/or TTF1, and presence of increased proliferative activity are features that can help in the distinction of anaplastic thyroid carcinomas." (PMID 32632840, 2020). "It induces the expression of differentiation markers (TTF1, TTF2, Pax8, and sodium/iodide symporter (NIS)) in anaplastic thyroid carcinoma through the activation of Notch1 signaling, thereby suppressing cell growth." (PMID 40943396, 2025). "Resveratrol, for example, has been shown to induce redifferentiation markers (TTF1, TTF2, Pax8, NIS) in anaplastic thyroid carcinoma cells through the activation of Notch1 signaling." (PMID 40943396, 2025). "Thyroglobulin and TTF1 can be negative when dedifferentiation to anaplastic thyroid carcinoma occurs." (PMID 32632840, 2020). "On the other hand, undifferentiated thyroid carcinomas, such as anaplastic carcinoma, are by definition thyroglobulin negative and almost always TTF1 negative." (PMID 27213120, 2016). "In addition, it might be difficult to distinguish anaplastic thyroid cancer from metastatic malignancies due to its poor differentiation and lack of expression of TTF-1." (PMID 24455357, 2013).
colorectal cancer (16 papers, 2006 to 2025). A primary or metastatic malignant neoplasm that affects the colon or rectum. "Currently, TTF-1 expression is standard for NSCLC subtype differentiation and NGS for genetic background, but this is not sufficient for pulmonary metastases (especially thyroid and colorectal carcinomas, which are sometimes positive for TTF-1 and BRAF mutation)." (PMID 39767631, 2024). "The overexpression of TTF1 was associated with poor prognosis in patients with colorectal cancer." (PMID 28938549, 2017). "This case highlights the need for a broad IHC panel and careful clinicopathologic correlation, as a small subset of colorectal cancers can aberrantly express TTF-1." (PMID 41310725, 2025). "Positive TTF-1 (especially clone 8G7G3/1) is also very rare in colorectal cancer and such tumours still tend to be CK20+/CK7-." (PMID 28347348, 2017). "Large series have shown that approximately 3–6% of colorectal carcinomas may also express TTF-1, particularly with the SPT24." (PMID 41310725, 2025). "Although a metastatic gastric tumor could have been highly suspected if TTF-1 had been evaluated at the time of biopsy, there are reports describing TTF-1-positive gastric cancer, colorectal cancer, or schwannoma." (PMID 36459241, 2022). "Moreover, the specificity of IHC is not always useful for distinction: e.g. TTF1 CK7, CDX2 and CK20 do not have any distinctive capacity between primary intestinal carcinoma from the lung and a metastasis from a colorectal carcinoma, as the IHC pattern is the same: TTF1-, CK7-, CDX2+ and CK20+." (PMID 31618260, 2019). "In addition to β-catenin, CK7, and CK20, thyroid transcriptional factor-1 (TTF-1) may be a useful marker for the discriminating diagnosis of lung metastasis of colorectal cancer and primary lung acinar adenocarcinoma." (PMID 16451736, 2006). "In contrast, gastrointestinal and colorectal cancers generally show negative immunostaining of TTF-1, and only 2.5% of colon cancers are reportedly positive for TTF-1." (PMID 29904902, 2018). "For example, a limited panel of thyroid transcription factor 1 (TTF-1) in combination with estrogen receptor and GATA3 or with cytokeratin (CK) 7 and CK20 normally separates lung cancer from breast cancer and colorectal cancer, respectively, with high accuracy." (PMID 28347348, 2017). "However, this study highlights that a small number of upper gastrointestinal adenocarcinomas (particularly poorly differentiated carcinomas) showed dual TTF-1/Napsin A positivity, while no colorectal cancers exhibited this pattern." (PMID 40564811, 2025).